CLEC3B (C-type lectin domain family 3 member B)
Diseases named in the same sentence as CLEC3B in open-access papers (continued):
Sharing a sentence is not in itself a finding about the gene and the disease.
tumor (33 papers, 2008 to 2025). "The antagonistic role of CLEC3B to tumor invasion seems to correspond to our finding that tumor ingrowth was hampered when the underlying dermis was constructed with PFs." (PMID 36232952, 2022). "C-Type Lectin Domain Family 3 Member B (CLEC3B) encodes proteins associated with tumor invasion and metastasis." (PMID 33553242, 2020). "This study was conducted to investigate the prognostic potential of CLEC3B and its association with tumor tissue infiltration markers." (PMID 33553242, 2020). "High-expression of SYNPR-AS1 and CLEC3B was associated with a better prognosis (P < 0.05), suggesting that they may act as tumor suppressors." (PMID 37537521, 2023). "In addition, CLEC3B was also highly expressed in normal samples and related to better OS while the rest six genes were highly expressed in tumor samples and associated with worse OS." (PMID 34416861, 2021). "Gene set enrichment analysis revealed tumor‐associated biological processes related to CLEC3B." (PMID 32265595, 2020). "Moreover, CLEC3B was related to tumor-associated macrophage (TAM) infiltration, which exerts both anti- and pro-tumor effects." (PMID 32265595, 2020). "The downregulation of CLEC3B promotes cell migration, invasion and epithelial-mesenchymal transition, and also affects tumor angiogenesis by regulating VEGF expression through the AMPK signaling pathway." (PMID 40496615, 2025). "The expression of CLEC3B mRNA in tumor tissue significantly decreased in paracancer bile duct tissue." (PMID 39553729, 2024). "Simultaneously, among the characteristic gene CLEC3B generated from the model, exosomes derived from HCC with downregulated CLEC3B were found to promote the migration, invasion, and epithelial-mesenchymal transition of both tumor cells and endothelial cells." (PMID 38812780, 2024). "The tumor volume was significantly smaller in the CLEC3B overexpressing group, indicating that CLEC3B can significantly inhibit the tumorigenesis of CCA cells." (PMID 39553729, 2024). "Through AMPK and VEGF signaling pathways, exosome CLEC3B can inhibit tumor metastasis and angiogenesis." (PMID 39553729, 2024). "FKBP4, TK1, HERPUD1, and CLEC3B levels were measured and verified in clinical samples (tumor tissues)." (PMID 37341998, 2023). "CLEC3B, a member of the C-type lectin superfamily, has been reported to be downregulated in serum and tumor tissues of HCC." (PMID 36213162, 2022). "CLEC3B can encode a protein localized within cell plasma, exosomes as well as extracellular matrix (ECM), and it is related to tumor metastasis and invasion." (PMID 33870858, 2021). "The Kaplan–Meier plotter was used to assess the prognostic value of CLEC3B transcriptional changes in tumor tissues." (PMID 33553242, 2020). "The results showed that CLEC3B expression was slightly correlated with ADC tumor purity but had a more significant correlation with tumor purity and immune infiltration levels of SCC." (PMID 32265595, 2020). "We used TIMER 2.0 to investigate the correlation between the expression of CLEC3B and infiltration levels of immune cells in 31 tumor tissues." (PMID 33553242, 2020). "The relationship between CLEC3B and tumor immune cell infiltration biomarkers was analyzed using TIMER." (PMID 33553242, 2020). "The expression of CLEC3B showed a notable correlation with the purity of the tumor in 20 tumor types." (PMID 33553242, 2020). "Other researchers found that downregulated CLEC3B promoted the migration, invasion, and epithelial–mesenchymal transition of tumor cells." (PMID 33553242, 2020). "Analysis of CLEC3B mRNA expression levels in normal and tumor tissues indicated that the expression of CLEC3B was notably downregulated in most tumors, with identical expression patterns in HCC in the different databases used." (PMID 33553242, 2020). "C-type lectin domain family 3 member B (CLEC3B) encodes a tetraspanin that acts by inducing fibrinogen activation, which is associated with tumor invasion and metastasis." (PMID 33134320, 2020).
tumor (continued). "In univariate analysis, larger tumour size, with pharmaceutical drug adjuvant therapy, high FNCLCC grade, increased COL11A1, ITGA10 and KIF26B expression, and decreased CLEC3B, DUOX2, KRT75 and PPP2R2B were risk factors of shorter RFS." (PMID 31742892, 2020). "Here, AMPK was proved as one of the common downstream signals of exosomal CLEC3B in both tumor cells and ECs." (PMID 31477130, 2019). "Exosomes derived from HCC with down-regulated CLEC3B promoted migration, invasion, epithelial–mesenchymal transition of both tumor cells and endothelial cells (ECs)." (PMID 31477130, 2019). "Further IHC assays attested that the expression of CLEC3B was negatively correlated with that of VEGF in HCC tumor tissues from patients or tumor implantation mouse." (PMID 31477130, 2019). "In vivo data showed that CLEC3Bhigh resulted in decreased intrahepatic metastasis and diminished tumor proliferation, which also revealed that CLEC3B suppressed HCC progression." (PMID 31477130, 2019). "Considering VEGF is a secreting protein, we analyzed the secreting levels of VEGF in tumor supernatants, and found that CLEC3B suppressed the secretion of VEGF." (PMID 31477130, 2019). "Immunohistochemistry (IHC) staining assay was performed in tissue microarrays of 80 pairs of HCC samples to reveal that the protein levels of CLEC3B was significantly decreased in tumor tissues." (PMID 31477130, 2019). "Mechanistically, CLEC3B-mediated VEGF expression in tumor cells and ECs depends on the activation of AMPK signal pathway." (PMID 31477130, 2019). "The vivo study indicated that CLEC3B inhibited tumor formation." (PMID 39553729, 2024). "The effect of CLEC3B on the tumor formation was proved by xenograft tumor model in nude mice." (PMID 39553729, 2024). "It suggests that CLEC3B inhibit the tumor formation in vivo." (PMID 39553729, 2024). "However, CLEC3B, co-expressed with a-SMA in cancer-associated fibroblasts in CRC, was indicated to be a tumor progressor." (PMID 39553729, 2024). "Compared with the GRIA1 gene, the biological role of the CLEC3B gene in tumor is more prominent." (PMID 35936688, 2022). "The results indicated a potential mechanism by which the CLEC3B expression might adjust tumor immunity by modulating the infiltration of immune cells in HCC patients." (PMID 33553242, 2020). "Thus, the downregulation of CLEC3B expression in tumor tissue contributes to carcinogenesis by uncontrolled proliferation of tumor cells." (PMID 33553242, 2020). "In addition, the protein expression of CLEC3B was investigated by IHC staining using a tissue microarray, which also showed that CLEC3B had lower expression in tumor tissues than peritumor tissues." (PMID 32265595, 2020). "However, the precise role of CLEC3B in tumor immune microenvironment and tumor progression still needs further research exploration." (PMID 32265595, 2020). "The relationship between CLEC3B tumor immune cell infiltration biomarkers was analyzed using TIMER." (PMID 33553242, 2020). "Our study demonstrated that CLEC3B could be a potential prognostic biomarker and might be involved in tumor immune cell infiltration in HCC." (PMID 33553242, 2020). "The function of exosomal CLEC3B in tumor progression were performed in vivo and in vitro." (PMID 31477130, 2019). "In our study, it may act as a tumor suppressor in that down-regulation of CLEC3B indicates a poor prognosis." (PMID 31396442, 2019). "Then we detected the expression of CLEC3B in HCC tumor (T) and peritumor samples (N), and found that CLEC3B was also significantly down-regulated at both mRNA (39 pairs) and protein (22 pairs) levels in tumors in quantitative real-time PCR analysis and in western blot." (PMID 31477130, 2019). "(B) Expression of proteins in tumor cells affected by CLEC3B." (PMID 31477130, 2019). "The function of CLEC3B depends on the location of the tumor." (PMID 31396442, 2019).
tumor (continued). "CLEC3B expression has negative correlation with proliferation inducers and proliferative markers, while there is a positive correlation between CLEC3B and proliferation inhibitors, indicating CLEC3B lowers cell proliferation, and may explain why it may serve as a tumor suppressor in OSCC." (PMID 31396442, 2019). "Unexpectedly, iCAF markers (CLEC3B and IL6) were largely and significantly upregulated in tumor tissues." (PMID 37444482, 2023). "CLEC3B, KLKB1, and LRG1 displayed significant difference at RNA level among the tumor stages and patient survival time." (PMID 32545216, 2020). "Down-regulated expression of CLEC3B in HCC patients was significantly related to tumor size, TNM stage, vessel metastasis and depth of invasion, which attested that CLEC3B expression was related to HCC progression, especially to metastasis." (PMID 31477130, 2019). "We performed meta-analysis on 8 microarray studies and identified six significantly up- (PLAU, FN1, CDCA5) and down-regulated (CRNN, CLEC3B and DUOX1) genes which were subsequently quantified by RT-qPCR in 100 HNSCC patient margin and core tumour samples." (PMID 31443700, 2019). "In conclusion, this study demonstrated that CLEC3B, which was down-regulated in HCC, acted as a tumor marker for poor prognostic factor for HCC patients and played a significant role in target cells and microenvironmental remodeling in HCC via exosomes." (PMID 31477130, 2019). "The correlation analysis on TCGA dataset revealed that CLEC3B was significantly correlated with VEGF in tumor tissues at mRNA level, and in vitro data also verified that mRNA levels of VEGF were reversely correlative to CLEC3B in HCC cells." (PMID 31477130, 2019). "CAFs secrete soluble factors, which include cytokines, chemokines, and growth factors such as interleukin 6 (IL-6), C-type lectin domain family 3 member B (CLEC3B), C-X-C motif chemokine 12 (CXCL12), and epidermal growth factor (EGF) to transform the TME to support tumor growth." (PMID 37469395, 2023). "Among a variety of tumor stage, the expression of FMO2 and CLEC3B differed significantly." (PMID 33870858, 2021). "In addition to the influences on tumor cells, we also observed that inhibition of p-AMPK lessened exosomal CLEC3B-mediated regulation of VEGF synthesis and secretion in ECs, as well as tube formation when directly treating ECs with exosomes from HCC cells." (PMID 31477130, 2019). "Similar with the effect on tumor cells, exosomal CLEC3B down-regulated mRNA expression and secretion of VEGF in ECs, and the cytoplasmic protein level of VEGF in ECs was decreased by exosomal CLEC3B either." (PMID 31477130, 2019). "Six loci (CLEC3B (previously TNA), MGP, RASSF1, SDK2, SERPINB5 and XAGE1A (previously GAGED2)) with statistically significantly higher methylation in tumor samples compared with non-tumor samples were identified." (PMID 18947422, 2008). "As for the HNSCC cell lines UM-SCC19 and UM-SCC47, they showed the opposite effect by downregulating the expression of CLEC3B and CCRL1 in the PFs (*** p < 0.001) after tumor cell-fibroblast co-culturing while not affecting the RF marker expression of TGM2 and MGP in the RFs." (PMID 36232952, 2022).
cancer (21 papers, 2007 to 2025). A tumor composed of atypical neoplastic, often pleomorphic cells that invade other tissues. "Since EMT played a vital role in originating migration and invasion of cancer cells, we detected relation between CLEC3B and EMT-associated genes." (PMID 31477130, 2019). "The ability of overexpression of CLEC3B to significantly inhibit cell migration and invasion has been confirmed in transwell experiment, while knocking down CLEC3B can enhance the migration and invasion of cancer cells." (PMID 39553729, 2024). "C-type lectins family member 3b (CLEC3B) is a Ca2+ binding transmembrane protein with different biological functions in a variety of cancers." (PMID 39553729, 2024). "More in-depth studies are still needed to clarify the molecular mechanism and function of CLEC3B in cancer progression." (PMID 37834257, 2023). "In this study, we used publicly available cancer databases to evaluate the prognostic and predictive role of CLEC3B expression, and to determine its correlation with the immune microenvironment phenotype." (PMID 32265595, 2020). "To investigate the role of CLEC3B in carcinogenesis, we first measured the transcription levels of CLEC3B mRNA in various types of cancer tissues by Oncomine analysis." (PMID 33553242, 2020). "In summary, CLEC3B plays a certain role in inhibiting the cancer progression in patients with CCA." (PMID 39553729, 2024). "Several studies reported that CLEC3B promotes myogenesis and inhibits cancer cellproliferation." (PMID 32696821, 2020). "Similarly, RNA-seq data collected from the TCGA database indicated that low expression of CLEC3B was detected in 17 types of cancers, including HCC." (PMID 33553242, 2020). "Recently, some studies revealed that CLEC3B is involved in human cancer progression as well." (PMID 31477130, 2019). "A reduced serum/plasma CLEC3B level is a biomarker for the metastasis of several human cancers." (PMID 30566430, 2018). "As results of initial validation by western blotting in relatively advanced cases and further validation including the less advanced cases by western blotting, the expression levels of the four proteins ApoA-IV, GC, RBP4, and CLEC3B were greater in cancer patients than in controls." (PMID 22091389, 2011). "In addition, the pharmacogenomic study of the DEPs in GSCA also showed that the downregulation of proteins such as PRDX4, GDI1, and YWHAE and the upregulation of proteins such as CLEC3B, KRT38, KRT37, and HNRNPCL1 were linked to higher sensitivity toward 30 pan-cancer CTRP drugs." (PMID 37900279, 2023). "Besides, CLEC3B seemed to play distinct roles in different human cancers." (PMID 34513664, 2021). "In contrast, the number of CTLs members namely CLEC3B, CLEC4G/M, and CLEC4E are decreased in cancer cells, which have the potential to be suppressor genes in different cancers." (PMID 38167030, 2024). "For example, ABCA5, ADAMTS12 and CLEC3B have not been reported to be cancer related." (PMID 21060876, 2010). "CRY1 has been implicated as a prognostic marker progression and survival in CLL and other types of cancer, however, the role of URAHP, MID1IP1, and CLEC3B has not been explored in CLL." (PMID 34187466, 2021). "Other proteins, such as CLEC3B, ITIH4, SAA1, and C20ORF3 exhibited increased expression in cancer EVs, while RBP4, SAA1, and DBP did not exhibit significant differences between normal and cancer samples." (PMID 33808296, 2021).
infection (4 papers, 2021 to 2025). The state of being infected such as from the introduction of a foreign agent such as serum, vaccine, antigenic substance or organism. "A number of non-infection associated genes that encode secreted proteins with potential to influence the phenotype of the infected cell and/or cells of the host immune system were also identified (e.g. IL9, CXCL2, CLEC3B and ADAMTS19)." (PMID 35061738, 2022). "In addition, we performed our proteome preparation by C18 enrichment method which could collect more small molecular proteins, and provided another insight for exploring infection-related small proteins, such as lung-enriched protein, CLEC3B." (PMID 33859163, 2021).
cardiovascular disease (3 papers, 2020 to 2022). "More recently, a 2018 biomarker analysis of the Framingham cohort in the US has shown that reduced circulating levels of Tetranectin (CLEC3B) are significantly associated with all‐cause mortality and with cardiovascular disease death." (PMID 32371911, 2020).
CLEC3B also shares sentences with these, for which no sentence is quoted: Sepsis (2 papers); squamous cell carcinoma (2); adenocarcinoma (1); angiosarcoma (1); Anxiety (1); connective tissue disorder (1); esophageal carcinoma (1); glioma (1); gout (1); head and neck squamous cell carcinoma (1); joint diseases (1); kidney cancer (1); liver disease (1); lymphoma (1); myocardial ischemia (1); pancreatic adenocarcinoma (1); preeclampsia (1); sarcoma (1); stomach cancer (1); tendinopathy (1); thyroid carcinoma (1).